IL6 (interleukin 6)
Diseases named in the same sentence as IL6 in open-access papers (continued):
Sharing a sentence is not in itself a finding about the gene and the disease.
infection (continued). "At 18 h and 96 h post infection (p.i.), no IFN-α, IL-6, CXCL10 or CCL2 was detected in the bronchoalveolar lavage fluid (BAL) of infected MTM−/− mice, in contrast to BAL from wt animals." (PMID 26688048, 2015). "In particular, a considerable number of the patients with infections but no fever had no increases in (WBC count, CRP and IL-6)." (PMID 24393388, 2014). "In this short-term prognostic analysis, the three infection-screening markers commonly used in medical laboratories (WBC count, CRP and IL-6) were not chosen as candidate predictors of mortality." (PMID 24393388, 2014). "As the downstream targets of NF‐κB activation, we found that inflammatory cytokines IL‐2, IL‐4, IL‐6, TNF‐α, and IFN‐γ were significantly increased in the infected organoids compared to the organoids without any infection." (PMID 25214524, 2014). "After infection, CD1c+ DCs expressed HLA-DR, CD40, and CD83 (top) and produced IL-6, TNF-α, and IL-1β but not IL-23, TGF-β, or IL-12p70 (F and data not shown)." (PMID 25071784, 2014). "Infection with L. major increased the secretion of TNF-α, IL-6, TIMP-1, IL-1RA, G-CSF and TREM, but not IL-1α or IL-1β." (PMID 24416445, 2014). "With this system, we noted differences in cytokines and chemokines, like FGF-Basic, IL-15, IL-6, IL-28A, ENA-78 and IP-10 without PBMCs and MIP-1β, IL-28A, MCP-2, and IFN-α with PBMCs between HRV 14 and 16 during infection of calu-3 cells." (PMID 25500821, 2014). "IGF-I increased production of IL-6 in uninfected macrophages, but while amastigote infection led to its decrease in IGF-I-stimulated cells, promastigote infection did not promote IL-6 decrease in IGF-I-stimulated cells." (PMID 25294956, 2014). "Although there was a trend for elevated levels of IL-1β, IL-6, and MCP-1 in CPEfat/fat mice 24 h post infection, none of these differences reached statistically significance." (PMID 25203099, 2014). "In concordance with previous studies, Fulani showed increased inflammatory mediators (IL-6, IFN-γ) and additionally also increased sCD163 levels compared to Dogon, irrespective of infection." (PMID 24274254, 2013). "After HCMV-infection, mild variations were observed for IL-8, MIP-1β and VEGF-A without reaching statistical significance and only IL-6 secretion was significantly increased in AD169-infected decidual fibroblasts (1.7 fold increase)." (PMID 23592985, 2013). "Given the results of the present study, it seems more likely that the CNS inflammatory response to acute inflammatory events elicited by infection, surgery or trauma, is being driven by TNF-α or IL-1β, rather than IL-6." (PMID 23840908, 2013). "The peak IL-6 level was most prominent in patients with SAI, while that of IL-17A was most apparent in PI patients without infection." (PMID 23936327, 2013). "In contrast to TNF-α we found IL-6 neither to induce apoptosis in the concentration range used, nor to enhance PICD after infection with E. coli." (PMID 23349721, 2013). "The infection state exhibits non-specific host responses, including immune responses such as changes in the concentrations of certain plasma proteins, cytokines (tumor necrosis factor, interleukin-1, interleukin-6) and interferon which may result in reduction of serum zinc level." (PMID 24353677, 2013). "Various combinations of IL-6, CRP and TNF-a can maintain sensitivities and negative predictive values above 90% for late-onset infection from presentation until 48 hours afterwards." (PMID 23869218, 2013). "None of the patients was observed to have an infection or inflammation during the observation period, and their CRP and IL-6 values were low (CRP 0.3 ± 0.6 mg/dL, IL-6 5.6 ± 4.0 pg/mL)." (PMID 23193472, 2012). "After NC infection, there was a trend towards higher levels of several cytokines and chemokines in DR1 than in B10 mice (IFN-γ and IL-6 for example), but differences were not statistically significant." (PMID 22457834, 2012).
infection (continued). "Infection of epithelial cells resulted in significantly increased secretion of the neutrophil chemotactic CXCL8 and IL-6, but no secretion of monocyte chemotactic CCL2 or TNF-α was observed." (PMID 22058091, 2012). "Elsewhere, CSF cytokines have been evaluated to diagnose infection in a variety of neurosurgical conditions and IL-1 and TNF were suggested to be of use, whereas IL-6 and IL-8 were not." (PMID 23176037, 2012). "Estimated frequencies of IL1B, TNF and IL6 two-locus (SNP) haplotypes in patients with prosthetic joint infection after total joint arthroplasty (TJA with PJI), those without infection (TJA without PJI) and Czech healthy controls." (PMID 22568934, 2012). "HCs were pretreated with or without IL-10, TGF-β, IL-4, IL-6, IFN-γ, and TNF-α prior to infection with HIV-1BaL." (PMID 23217137, 2012). "Compared to the infected wild-type mice, the mRNA expression levels of IL-1β, IL-6, and TNF-α as well as the number of infiltrating immune cells revealed no distinction in STAT3 KO mice 10 days after infection." (PMID 22675647, 2012). "Gastric epithelial MKN7 cells produced the pro-inflammatory cytokines IL-6 and IL-8, but not IL-1β, IL-10, IL-12p70 or TNF (data not shown), after infection with H. pylori J99." (PMID 22563496, 2012). "Significantly higher values between the infection and noninfection groups were seen for CRP, IL-6, WBC, I/T ratio, PCT, and CT." (PMID 22685675, 2012). "The extent to which a small inoculum or transient infection might impact the mother or fetus' health is unknown, but may reflect the most common event leading to preterm birth in the setting of intrauterine inflammation [elevated amniotic interleukin-6 (IL-6)] and a negative amniotic fluid culture." (PMID 22216148, 2011). "As predicted, IL-6-/- mice failed to mount a Th17 response and instead developed IFN-γ+ T cells following intranasal infection." (PMID 21966268, 2011). "In the MDDC alone supernatant only low amounts of TNF-α, IL-6, MIP-1α and MIP-1β were found after MVA and MVA-B infection (data not shown)." (PMID 21625608, 2011). "Among the different cytokines analyzed in our study, the sera levels of IL-6 and IL-10 were considerably higher in the P(H1N1) patients than that of the non-ILIs infection patients and the healthy controls." (PMID 22174866, 2011). "Plasma cytokine levels were either not different between the groups (TNF-α, IL-6, IFN-γ) or below detection (MCP-1, IL-12, IL-10) at both 24 and 48 hours after infection (data not shown)." (PMID 20682036, 2010). "This is especially significant because it was at day 5 post infection, when IL-6 levels were highest, that mice lacking P58IPK died from infection." (PMID 19461876, 2009). "Our findings suggest that an elevated concentration of IL-6 in the amniotic fluid may be a specific marker of infection/inflammation in the amniotic cavity, whereas infection/inflammation isolated to the maternal compartment may not be sufficient to elevate amniotic fluid IL-6 concentrations." (PMID 19857262, 2009). "Further, these data suggest that IL-6 and IFN-γ do not play a critical role in the survival of mice following CB4 challenge as MyD88KO mice survived infection and controlled viral replication despite reduced levels of both of these cytokines." (PMID 19122812, 2009). "The cytokines are divided into two important groups: theproinflammatory such as IL-1, IL-6, and TNF-α, and the anti-inflammatory such as IL-10,and have a negative impact on resistance to infection and in septic mice,reduction of IL-10 levels improves survival." (PMID 18604304, 2008). "Selenium and parameters of infection or inflammation have been recently described as a situation of negative correlation between Se and CRP and IL-6." (PMID 18221503, 2008). "The expression of il6 and ifng were significantly enhanced in the presence of XIAP during infection, while expression of tnf and ifnb were not altered." (PMID 18769721, 2008).
infection (continued). "The cytokine profile measured in BALF from adult and weanling mice mirrored the inflammatory profile, with adult mice showing increased levels of TNFα, IFNγ, MCP-1, IL-6 and VEGF at 7 d post infection but not at 5 d (not measured at 10 d)." (PMID 16324223, 2005). "In keeping with inflammatory cell numbers, weanling mice did not have elevated TNFα, IFNγ, MCP-1 or IL-6 in BALF at any timepoint, although VEGF was elevated at 7 d post infection." (PMID 16324223, 2005). "In the presence of AAV-siRNA infection, the production of IFN-γ, TNF-α, IL-8, IL-6, and IL-12 did not change significantly compared with cultured DCs." (PMID 15301687, 2004). "In a non-lethal infection model, azeliragon markedly reduced bacterial loads in blood and lung tissues and significantly decreased serum levels of pro-inflammatory cytokines, including TNF-α and IL-6." (PMID 42040546, 2026). "IL-6 and IL-10 secretion was not altered by TLR7/8 stimulation prior to infection." (PMID 41974867, 2026). "Interestingly, unlike previous studies that reported upregulation of IL-6 during highly virulent PRRSV infections such as HP-PRRSV, IL-6 levels in this study gradually decreased, particularly in JBNU-22-N01 infection." (PMID 40459260, 2025). "When we examined the expression levels of inflammatory cytokines and interferons, we found that the expression levels of interleukin-1 beta (IL-1β), interleukin-6 (IL-6), tumor necrosis factor (TNF-α), interferon beta (IFN-β), and interferon lambda-1 (IFN-λ1) were not altered by MPXV infection." (PMID 41542170, 2025). "In the absence of infection, offspring of LFD- and HFD-fed dams exhibited significantly reduced serum levels of key cytokines involved in innate immunity, including G-CSF, GM-CSF, IL-6, and IL-10, compared to CD-fed dam offspring." (PMID 40766470, 2025). "However, serum and tissue levels of CXCL1/KC and IL-6 were elevated during infection, and both AZD5148 and bezlotoxumab were effective in lowering CXCL1/KC and IL-6 levels in sera (p < 0.0001), but not in tissue." (PMID 41183070, 2025). "However, serum levels of TNF-α, IL-6, and IFN-γ were significantly higher in the infection group than in the non-infection group, with statistically significant differences (P<0.05)." (PMID 40677522, 2025). "Infection of BALB/c and STS mice resulted in 10-500× increase of production of IFNγ IL-2, IL-4, IL-6 and IL-10 by their splenocytes, whereas strain O20 splenocytes did not produce any of these cytokines except IL-6." (PMID 41164189, 2025). "For LR04 CFS, all the 20% concentrations did not reduce IL-6 production upon infection, except for the TIL-produced CFS + vitamin D (p < 0.01 vs. infection control), which was more effective than TIL-CFS alone (p < 0.0001) and better than the same condition in MRS (p < 0.001)." (PMID 40351306, 2025). "Together, these data show that IL-6 (but not CD4+ cells) contributes to the initial awakening and expansion of dormant DCCs, but that later during the infection, following the recruitment of T cells, CD4+ cells are required for the maintenance of the awakened DCCs." (PMID 40739350, 2025). "This persistent, subclinical inflammation, termed “inflammaging”, is characterized by modest but sustained elevations of circulating cytokines such as interleukin-6 (IL-6), tumor necrosis factor alpha (TNF-α), and C-reactive protein (CRP), even in the absence of infection." (PMID 41373468, 2025). "Another study found that inflammatory markers such as IL-6, C-reactive protein (CRP), ferritin, lactate dehydrogenase (LDH), and D-dimer were found to be highly elevated in severe and critical COVID-19 infection as opposed to mild infection." (PMID 40376340, 2025). "Prior research supports this possibility: ethacridine lactate in wound models selectively inhibited IL-6 and IL-10 while boosting IL-12 and IFN-γ, effectively skewing the response toward a pro-inflammatory, infection-clearing profile without immunosuppressive effects." (PMID 41150817, 2025).
infection (continued). "As it is a non-specific serum indicator of inflammation, IL-6 may yield false positives when trying to detect PJI, for example, in cases of injury, trauma, stress, infection, brain death and other situations." (PMID 40981112, 2025). "The MOIs of 0.1 and 1 used to treat endothelial cells produced significant amounts of pro-inflammatory cytokines IL-6 and CCL2, so the MOI of 1 was chosen for the subsequent experiments as a way to mirror direct infection of brain endothelial cells, but not microglia and astrocytes." (PMID 39474424, 2024). "Cytokines known as inappetence-inducing factors including IL-6, IL-1β, TNF, and IFN-g were not significantly different in the brain after infection, whereas IL-1α was significantly reduced (P < 0.0001) in the brain of both αCD8α treated and aIL-1a treated mice compared to RSV treated." (PMID 38382577, 2024). "On the opposite, the strong stimulatory effect of OMVs on IL-6 and the chemokine CXCL-1 secretions always predominated the suppression induced by infection no matter whether BMMs were infected before or after OMVs treatment." (PMID 38533334, 2024). "IL-6 and TNF-α did not change significantly up to 8 days after M. gallisepticum strain Rlow infection, except that IL-1 was significantly up-regulated at 3 days post-infection." (PMID 38474071, 2024). "Concluding, 5-month-old NSPHs are immune responsive to pro-inflammatory stimulation and SeVeGFP-infection, as demonstrated by the secretion of IL-6 and CXCL10, but do not secrete pro-inflammatory cytokines following VZVeGFP-ORF23-infection, at least not for the panel applied in this study." (PMID 39351233, 2024). "Inflammatory cytokines, such as IL-6, IL-8, and MCP-1 levels, were higher in human embryonic lung fibroblast cells (MRC-5) infected by rAdV3E-K7 and rAdV3E-K55 than those by rAdV3E both at 10 and 26 h post-infection (data not shown)." (PMID 38018973, 2024). "Interestingly, a study by Taglauer and colleagues (2022) indicated persistent elevated levels of IL-6 and IL-8 at delivery after SARS-CoV-2 infection in early pregnancy, but not after infection in late pregnancy." (PMID 38522364, 2024). "The levels of proinflammatory cytokines (IP-10, IL-1β, IL-6, IL-8, TNF-α and GM-CSF) and anti-virus-related factors (IFN-α, IFN-λ1 and IFN-γ) were upregulated in the blood samples of the six patients as compared those of the control patients without infection." (PMID 37090924, 2023). "However, the serum C-reactive protein, IL-6, PCT level of infection-related group were significantly higher than that of noninfectious RP-DPLD patients (all p<0.05)." (PMID 37408612, 2023). "Anti-infection treatment may also affect NLR, and the lack of data on other inflammation indicators, such as CRP and IL-6, is another limitation." (PMID 37457569, 2023). "As opposed to the synovial protein, the plasmatic concentration of PTX3 had poor diagnostic value, likely due to this long pentraxin being mainly synthesized in loco at sites of infection, unlike the short pentraxin CRP that is systemically produced by the liver in response to IL-6." (PMID 36769703, 2023). "The absence of IL-6, MCP-1, or IL-17 did not impact the growth of ΔplaY. pestis relative to WT bacteria, indicating that neither of these cytokines alone drives responses capable of controlling infection." (PMID 37338372, 2023). "Interestingly, unlike CRP, serum levels of PCT, IL-6, and IL-10 in the GN-BSI group were consistently higher than those in the GP-BSI group at all time points during 48 h post-infection." (PMID 37986183, 2023). "However, comparisons between vaccinated mice showed that H7N7 infection did not significantly increase levels of CCL2 (p = 0.94), IFNγ (p = 0.97), IL1β (p = 0.52), and IL-6 (p = 0.59) in the lungs compared to vaccinated mice receiving PBS." (PMID 37063291, 2023).
infection (continued). "Instead, infection with the virulent 22653/14 ASFV did not alter any surface marker expression and did not trigger the release of either IFNβ, anti-inflammatory IL-10, proinflammatory (IL-1β, IL-6, IL-8, TNF-α), and pro-Th1 (IL-12, IL-18) cytokines." (PMID 35215216, 2022). "However, therapeutic treatment with Ac2–26, given as a single dose at 24 h post-infection, was not sufficient to decrease MPO, CXCL1, or IL-6 levels in mice compared with untreated WT (BALB/c) animals." (PMID 36078125, 2022). "Interestingly, IL-6 and MCP-3 showed a delayed increase until week 1 (days 6–10) post-infection in the non-vaccinated group and 1-dose group." (PMID 35810174, 2022). "Analysis of cytokines produced by ZIKV-stimulated baboon PBMC showed that expression of IL-6 was significant before challenge with ZIKV UG, almost after 6 months post-infection with ZIKV PR, and did not change significantly immediately after challenge with ZIKV UG." (PMID 35493734, 2022). "However, we observed no induction of TNF-α following infection of ARPE-19 or primary retinal pigment epithelial cells with DENV-1 strains, and induction of IL-6 in infected ARPE-19 cells alone." (PMID 35208767, 2022). "Furthermore, knockdown of Nek7 significantly inhibited the secretion of IL-1β, but the secretion of IL-6, TNF-α, and IL-1α were not affected during PmCQ2 infection." (PMID 35350616, 2022). "IL-1β was observed with a significant decrease in the supernatant of SFTSV infected NLRP3 KO THP-1 cells 48 h after infection compared with the wild type THP-1 cells, while no significant change of TNF-α and IL-6 was detected in the NLRP3 KO cells compared with wild type cells." (PMID 33708197, 2021). "Interestingly, IL-1β, IL-6, IL-10 and IL-12 were not significantly altered upon DAF depletion over the course of infection." (PMID 34197564, 2021). "Similarly to previously published work, the expression of the inflammatory cytokines (IL-1β, IL-6, IL-8, and TNF-α) after RVFV infection was upregulated to a greater extent in the absence of the RVFV NSs protein." (PMID 34835071, 2021). "In addition, we found that IL-6 and IL-10 levels, rather than viral load and neutralizing antibody titers, in patients with an SFTSV infection strongly correlated with outcomes (for severe disease with an ultimate outcome of recovery or death)." (PMID 34484214, 2021). "Although ML decreased IL-6 expression level in the absence of PEDV infection, and it also decreased the expression of IL-6 and IL-8 induced by PEDV, supporting the immunoregulatory effect of ML during infection." (PMID 35095875, 2021). "The production of proinflammatory cytokines CXCL10 and IL-6 increased in both HRV16 and HRV1B infection (p < 0.05 for each), whereas IL-8 and IL-18 production increased in HRV1B infection (p = 0.025 and p = 0.018, respectively), but not in HRV16 infection (p = 0.314 and p = 0.674, respectively)." (PMID 34838080, 2021). "Besides, the infection resulted in decreased production of IL-12 and TNF, but not IL-6, at 24 h and 48 h." (PMID 34354963, 2021). "IL-6 level was affected by both culture outcome and pathogen number, indicating that FRI patients with positive culture outcomes and polymicrobial infections had significantly higher levels than those with negative outcomes (P = 0.016) and monomicrobial infections (P = 0.049), separately." (PMID 34595243, 2021). "Moreover, the plasma levels of IL-2, IL-6, IL-8, IL-10, and TNF-α, observed in severe infection, are prominently greater than those with nonsevere infection." (PMID 34844296, 2021). "There was prominent induction of IL-6, CCL3, and CCL4 in genotype 1 infected decidua and placenta compared to genotype 3 while expression of TNF-α, IL-15, IL-18, and CCL-5 was barely detected regardless of infection." (PMID 34502167, 2021).